IRAG2 (inositol 1,4,5-triphosphate receptor associated 2)
Description:
Plays a role in the delivery of peptides to major histocompatibility complex (MHC) class I molecules; this occurs in a transporter associated with antigen processing (TAP)-independent manner. May play a role in taste signal transduction via ITPR3. May play a role during fertilization in pronucleus congression and fusion. Plays a role in maintaining nuclear shape, maybe as a component of the LINC complex and through interaction with microtubules. Plays a role in the regulation of cellular excitability by regulating the hyperpolarization-activated cyclic nucleotide-gated HCN4 channel activity (By similarity).
Synonyms: JAW1; LRMP
Tractability: Antibody: its Gene Ontology location is reachable by antibodies, with high confidence; UniProt predicts a signal peptide or a membrane-spanning region; the Human Protein Atlas places it where antibodies can reach. PROTAC: ubiquitination databases record sites on it.
Gene: Protein-coding gene on chromosome 12 (25,004,342 to 25,108,489, forward strand). Ensembl gene ENSG00000118308.
Subcellular location: Cytoplasm (Processed inositol 1,4,5-triphosphate receptor associated 2); Endoplasmic reticulum membrane; Nucleus envelope; Cytoplasm, cytoskeleton, microtubule organizing center, centrosome; Cytoplasm, cytoskeleton, spindle pole; Chromosome
Subcellular location (Human Protein Atlas): Endoplasmic reticulum; Plasma membrane
Pathways (Reactome):
Immune System: Neutrophil degranulation
Gene Ontology:
Molecular function: protein binding; microtubule binding
Biological process: nucleus organization
Cellular component: endoplasmic reticulum membrane; meiotic nuclear membrane microtubule tethering complex; membrane; azurophil granule membrane; chromosome; cytoplasm; nuclear envelope; plasma membrane; centrosome; spindle pole
Genetic constraint (gnomAD): Loss-of-function variants: 28 observed, 46.4 expected, observed/expected ratio (o/e) 0.6, 90% interval 0.45 to 0.83. The upper end of that interval is the gene's LOEUF score, 0.83, which puts it in group 3 of 6, group 1 being the genes least tolerant of losing a copy. Missense variants: 354 observed, 431.51 expected, observed/expected ratio (o/e) 0.82, 90% interval 0.75 to 0.9. Synonymous variants: 137 observed, 152.05 expected, observed/expected ratio (o/e) 0.9, 90% interval 0.78 to 1.04.
Homologues: Orthologues: chimpanzee IRAG2 (99% identical), macaque IRAG2 (95% identical), dog IRAG2 (85% identical), rabbit IRAG2 (79% identical), guinea pig IRAG2 (76% identical), mouse Irag2 (70% identical), rat Irag2 (70% identical), tropical clawed frog irag2 (42% identical), zebrafish lrmp (36% identical). Paralogues in human: IRAG1 (21% identical).
Diseases named in the same sentence as IRAG2 in open-access papers:
IRAG2 is named in the same sentence as 24 diseases in open-access papers, as found by Europe PMC text mining. Sharing a sentence is not in itself a finding about the gene and the disease. The quoted sentences say what the papers report.
diffuse large B-cell lymphoma (3 papers, 2010 to 2023). "Lymphochip array studies revealed that IRAG2 is one of the GC genes whose overexpression defines the good-prognosis GC subcategory of diffuse large B-cell lymphoma (DLBCL)." (PMID 37372987, 2023).
B-cell lymphomas (2 papers, 2007 to 2023). "This immunohistology analysis of IRAG2 also focused on hematolymphoid neoplasia-like lymphomas, where IRAG2 expression was detectable in B-cell lymphomas but not in T-cell neoplasms." (PMID 37372987, 2023).
diabetes (2 papers, 2021 to 2023). "For IRAG2, polymorphisms are coupled to the risk of cancer diseases, e.g., lung tumors, diabetes, or immune diseases." (PMID 37372987, 2023). "Additionally, a high number of IRAG2 SNPs is found on this locus in non-obese-diabetes (NOD) mice, which contributes to the thesis that IRAG2 might have an impact on the development of diabetes." (PMID 37372987, 2023). "Additionally, it is reported that the idd6 diabetes susceptibility region controls defective expression of the IRAG2 gene in NOD mice, where the NOD allele at this locus mediates lower mRNA expression levels of IRAG2." (PMID 37372987, 2023).
lung adenocarcinoma (2 papers, 2021 to 2023). A carcinoma that arises from the lung and is characterized by the presence of malignant glandular epithelial cells. "Thereby, it is shown that the IRAG2 gene and protein expression is lower in patients with lung adenocarcinoma as well as in lung adenocarcinoma cell lines." (PMID 37372987, 2023). "Recently, IRAG2 expression was examined in lung adenocarcinoma." (PMID 37372987, 2023). "Furthermore, expression of IRAG2 was detected in normal human lung tissue and human lung adenocarcinomas, as well as in mouse normal lung tissue and mouse lung tumors." (PMID 37372987, 2023). "Hence, IRAG2 could also be involved in the immunotherapy response of lung adenocarcinoma patients using checkpoint inhibitors." (PMID 37372987, 2023). "A hypothesis for the impact of the Val141Leu SNP on the survival rate might be an altered modulation of patients’ immune systems, as it was recently suggested that IRAG2 might act as a tumor suppressor that is involved in the progression of lung adenocarcinoma (s." (PMID 37372987, 2023). "Thereby, no obvious differences between normal lung and lung adenocarcinoma tissue in IRAG2 expression levels were observed." (PMID 37372987, 2023).
lymphoma (2 papers, 2007 to 2023). A malignant (clonal) proliferation of B- lymphocytes or T- lymphocytes which involves the lymph nodes, bone marrow and/or extranodal sites. "Additionally, IRAG2 is expressed in lymphomas arising from germinal centers, Burkitt’s lymphoma, and lymphocyte-predominant Hodgkin’s disease." (PMID 37372987, 2023).
type 1 diabetes (2 papers, 2021 to 2023). "This leads to the hypothesis that decreased expression of IRAG2 in these NOD mice might constitute a type 1 diabetes susceptibility factor in this Idd6 region." (PMID 37372987, 2023). "Upregulated expression of IRAG1 was associated with a bad prognosis of solid tumors, whereas the high expression level of IRAG2 could be a beneficial marker for the prognosis of lung tumors or the development of type 1 diabetes." (PMID 37372987, 2023).
acute pancreatitis (1 paper, 2023). An acute inflammatory process that leads to necrosis of the pancreatic parenchyma. "As premature activation of digestive enzymes in the acinar cells contributes to the emergence of acute pancreatitis, IRAG2 might also reveal a protective effect against pancreatic diseases, such as acute pancreatitis." (PMID 37372987, 2023).
Hodgkin’s disease (1 paper, 2023). "Further, IRAG2 is detectable in almost all chronic lymphatic leukemias but not in classical Hodgkin’s disease." (PMID 37372987, 2023).
ovarian carcinoma (1 paper, 2023). A malignant neoplasm originating from the surface ovarian epithelium. "Preliminary studies also showed the expression of IRAG2 in some cases of ovarian cancer, which suggests that IRAG2 may represent a potential marker in the field of ovarian cancer." (PMID 37372987, 2023).
pancreatic diseases (1 paper, 2021). "However, the accumulation of amylase in pancreata from IRAG2-KO mice could contribute to pancreatic diseases like pancreatitis." (PMID 34948204, 2021). "Therefore, IRAG2 could have a protective effect against pancreatic diseases." (PMID 34948204, 2021).
platelet disorders (1 paper, 2023). "Hence, lack of IRAG1 or IRAG2 leads to diverse phenotypes in these organs, e.g., smooth muscle and platelet disorders or secretory deficiency, respectively." (PMID 37372987, 2023).
tumor (6 papers, 2011 to 2025). "IRAG2 is also positively associated with various tumor-infiltrating immune cells and their markers." (PMID 37372987, 2023). "Regarding tumor diseases, it is noteworthy that both IRAG1 and IRAG2 were reported to possibly act as tumor suppressor genes." (PMID 37372987, 2023).
cardiovascular diseases (1 paper, 2022). "As IRAG2 appears to enhance aggregability of platelets, IRAG2 might have a potential role in the formation of thrombi and therefore in atherogenesis and development of cardiovascular diseases." (PMID 35743138, 2022).
IRAG2 also shares sentences with these, for which no sentence is quoted: cancer (6 papers); parasitic infections (3); breast carcinoma (1); colon cancer (1); follicle centre lymphoma (1); immune diseases (1); infection (1); melanoma (1); pancreatitis (1); T-cell neoplasms (1); triple-negative breast carcinoma (1).